SPRY4 (sprouty RTK signaling antagonist 4)
Diseases named in the same sentence as SPRY4 in open-access papers (continued):
Sharing a sentence is not in itself a finding about the gene and the disease.
hepatocellular carcinoma (4 papers, 2019 to 2024). A malignant tumor that arises from hepatocytes. "In prostate, colorectal, and hepatocellular carcinomas the SPRY4 transcript has been shown to be lower in comparison to the respective normal tissues." (PMID 34048471, 2021). "Currently, there are fewer studies on SPRY4 in hepatocellular carcinoma (HCC)." (PMID 38686189, 2024). "In hepatocellular carcinoma-resistant patients, histone deacetylase 4 (HDAC4) modifies the chromatin configuration within the SPRY4 promoter region, leading to transcriptional inhibition of the SPRY4 gene." (PMID 38686189, 2024). "Likewise, SPRY4 suppression occurs in hepatocellular carcinoma drug-resistant patients, where histone deacetylase 4 (HDAC4) modifies the histone configuration within the SPRY4 promoter region, resulting in a heterochromatin (silenced) state." (PMID 36384366, 2023).
hypogonadotropic hypogonadism (4 papers, 2018 to 2025). Abnormal ovarian or testicular function due to insufficient hormonal stimulation from the hypothalamic-pituitary axis. "One variant was found in the SPRY4 gene (c.55C > G; p.(Gln19Glu)), which is associated with hypogonadotropic hypogonadism, where the congenital form was also linked to oligogenic inheritance." (PMID 40037090, 2025). "A frequently with congenital hypogonadotropic hypogonadism-associated alteration affecting the Raf-binding domain of Spry4 was shown to be a hyperactive inhibitor of cell proliferation and migration." (PMID 40806483, 2025). "Recently, mutations in the Spry4 were discovered to be associated with congenital hypogonadotropic hypogonadism." (PMID 40806483, 2025).
schizophrenia (3 papers, 2008 to 2020). A major psychotic disorder characterized by abnormalities in the perception or expression of reality. "Finally, SPRY4 was previously found differentially methylated in the blood of patients diagnosed with schizophrenia." (PMID 31931860, 2020). "Together, these results suggest that alterations within SPRY4 could contribute to psychiatric disorders such as depression, PTSD, and schizophrenia and potentially play a role in suicidal behavior." (PMID 31931860, 2020).
asthma (2 papers, 2022). "Interestingly, five of these loci, i.e., ACTN1, PDS5B, SEMA6D, SPRY4, and TENM3, have been reported of association with the genetic susceptibility of asthma." (PMID 36051697, 2022).
Brain Tumors (2 papers, 2019 to 2020). "CIC was found to be expressed in several GBM and primary brain tumor-initiating cell (BTIC) lines despite exhibiting increased expression of CIC target genes downstream of MAPK (ETV1/4/5, DUSP6, SPRY4), compared to NHA cells." (PMID 33115448, 2020).
colon carcinoma (2 papers, 2019 to 2025). "It has also been shown that proliferation of colon cancer-derived cells slows down in the presence of Spry4." (PMID 40806483, 2025). "An opposing role of Spry4 to other Spry proteins is already signified in colon carcinomas." (PMID 31374860, 2019).
depression (2 papers, 2017 to 2020). "Administration of FGF9 to male rats increases anxiety and depression-like behavior, and FGF9 stimulates expression of SPRY4 in vitro." (PMID 29096718, 2017).
esophageal cancer (2 papers, 2021 to 2023). A primary or metastatic malignant neoplasm involving the esophagus. "The same function was observed in esophageal carcinoma by regulating SPRY4 and HOXB13 expression." (PMID 36624401, 2023). "LncRNA ENST00000500112 (LncRNA CCAT1), which was upregulated in CRC and esophageal cancer, by adjusting the expression of HOXB13 and SPRY4 affect cell proliferation and migration in esophageal squamous carcinoma." (PMID 33493136, 2021).
gastrointestinal stromal tumor (2 papers, 2015 to 2023). "In contrast, SPRY4 is upregulated and may serve an oncogenic function in gastrointestinal stromal tumors (GIST)." (PMID 36384366, 2023).
hypogonadism (2 papers, 2018 to 2019). A disorder characterized by decreased function of the gonads. "We identified a single variant, predicted to be damaging by in silico tools, in the SPRY4 (sprouty RTK signaling antagonist 4) gene in a 46,XY male patient (CDSD039) with hypogonadism." (PMID 29378665, 2018).
metastatic melanoma (2 papers, 2015 to 2019). A melanoma that has spread from its primary site to another anatomic site. "SPRY4 expression is diminished in metastatic melanoma compared to primary tumors." (PMID 26392417, 2015).
Obesity (2 papers, 2022 to 2025). Accumulation of substantial excess body fat. "Our findings provide new insights into a critical role for SPRY4 as a regulator of adipogenic differentiation, which may illuminate the underlying mechanisms of obesity and suggest the potential of SPRY4 as a novel treatment option." (PMID 36082406, 2022). "Certainly, in order to find more precise targets for obesity treatment, further studies are required to elucidate the specific mechanism by which SPRY4 activates the ERK1/2 signalling pathway." (PMID 36082406, 2022). "Our findings reveal the contribution of SPRY4 to hAMSC adipogenesis, and further identification of the cell type-specific signalling pathways in hAMSC adipogenesis, will help to expand the treatment options for combating obesity and the related health complications." (PMID 36082406, 2022).
osteoarthritis (2 papers, 2021 to 2024). A noninflammatory degenerative joint disease occurring chiefly in older persons, characterized by degeneration of the articular cartilage, hypertrophy of bone at the margins and changes in the synovial membrane. "We conclude that SPRY4 is a crucial indicator of osteoarthritis (OA) severity and could play an important role in preventing OA in the cartilage by inhibiting chondrocyte hypertrophy." (PMID 34535669, 2021). "The same relationship between SPRY4 expression levels and OA was also observed in the DMM animal model that mimicked the osteoarthritis bio environment." (PMID 34535669, 2021).
pancreatic carcinoma (2 papers, 2021 to 2022). "Furthermore, scatter plot analyses showed significant positive correlations of SET/CIP2A expression with the expression levels of the IEGs (TRIB1, SPRY4, CTGF) and with those of growth-promoting genes (cyclin D1, E2, and PCNA) in KRAS-mutated pancreatic cancers." (PMID 36463234, 2022). "In cells derived from prostate and pancreatic carcinoma, Spry4 is inhibiting cell migration without affecting the proliferation of the cells." (PMID 33670044, 2021).
seminoma (2 papers, 2016 to 2018). A radiosensitive malignant germ cell tumor found in the testis (especially undescended), and extragonadal sites (anterior mediastinum and pineal gland). "A profound difference of SPRY4 protein expression between moderately differentiated seminoma and undifferentiated seminoma was observed, with the highest level in undifferentiated seminoma." (PMID 29410498, 2018). "Particularly, no detection of SPRY4 protein in any normal testis sample, and the profound difference of SPRY4 protein expression between moderately differentiated seminoma sample and undifferentiated seminoma sample indicate that SPRY4 may act as an oncogene in TGCT pathogenesis." (PMID 29410498, 2018). "We found lower RNA expression levels of SPRY4 and SPRY4-IT1 in seminoma than in other TGCT subtypes but had no information about the status of differentiation of these two seminoma samples." (PMID 29410498, 2018).
Sepsis (2 papers, 2024). Sepsis is defined as life-threatening organ dysfunction caused by a dysregulated host response to infection. "The overexpression of macrophage Spry4 intensifies inflammation, oxidative stress, and lung injury in septic mice, whereas Spry4 deficiency mitigates sepsis-induced lung injury by activating the CaMKK2/AMPK pathway." (PMID 39712019, 2024). "Researchers have found that overexpression of macrophage SPRY4 exacerbates sepsis-induced acute lung injury, leading to increased inflammation scores and impaired lung function." (PMID 38686189, 2024). "During sepsis, mice with macrophage SPRY4 overexpression exhibited increased levels of reactive oxygen species (ROS) in lung tissue." (PMID 38686189, 2024). "Moreover, research has established that macrophage Sprouty4 (Spry4) and SAMSN1 modulate sepsis-induced lung injury via the AMPK pathway." (PMID 39712019, 2024).
testicular cancer (2 papers, 2012 to 2014). A primary or metastatic malignant neoplasm that affects the testis. "141691500G>T) and a germline mutation rs72117814 within a predicted binding site for miR-608 in the 3′UTR of SPRY4 which was located in the same linkage disequilibrium block as rs4624820, a high-ranking marker in a testicular cancer GWAS." (PMID 23091610, 2012). "SPRY4 inhibits the mitogen-activated protein kinase pathway (MAPK) which is activated by the KITLG-KIT pathway, which has been associated with testicular cancer." (PMID 23091610, 2012).
thyroid cancer (2 papers, 2023 to 2024). "SPRY4 induces macrophage-induced protrusion formation and cytoskeletal changes in undifferentiated thyroid cancer cells, thereby increasing cancer cell invasiveness." (PMID 38686189, 2024). "SPRY4 may act as a mediator of communication between macrophages and undifferentiated thyroid cancer cells, exerting tumor-suppressive effects." (PMID 38686189, 2024). "This target was of particular interest, first due to its role in MAPK signaling, a crucial pathway in thyroid cancer, and in addition, our group had previously identified SPRY4 as a novel candidate susceptibility gene for familial nonmedullary thyroid cancer (FNMTC)." (PMID 37686663, 2023). "Comparing this study in well-differentiated thyroid cancer cells with the present results in ATC cells, it appears that SPRY4 may have an opposite role in these subtypes of thyroid cancer." (PMID 37686663, 2023). "Previous functional in vitro studies developed by our group showed that siRNA-mediated SPRY4 gene silencing induced a significant decrease in TPC-1 viable cells, suggesting that this gene may have an oncogenic activity in follicular-cell-derived thyroid cancer." (PMID 37686663, 2023).
brain cancer (1 paper, 2019). A primary or metastatic malignant neoplasm affecting the brain. "To investigate if Spry3 and Spry4 interfere with cell proliferation in brain cancer-derived cells, we selected DBTRG-05MG and U373 cell lines to apply ectopic overexpression of the respective Spry proteins." (PMID 31374860, 2019). "In this study we provide data showing that Spry3 and Spry4 expression may be altered in brain cancer and affect cell proliferation and migration in opposing ways." (PMID 31374860, 2019). "In summary, our study describes that Spry3 and Spry4 exert different roles in brain cancer." (PMID 31374860, 2019). "Ectopic expression of Spry4 inhibited proliferation and migration of GBM-originated cells, positioning it as a tumor suppressor in brain cancer." (PMID 31374860, 2019).
cervical cancer (1 paper, 2023). A primary or metastatic malignant neoplasm involving the cervix. "In summary, SPRY4 and HOTAIR among lncRNAs are promising markers of cervical cancer, which can be used as diagnostic indicators and good markers for prognosis of cervical cancer." (PMID 36890809, 2023).
cholangiocarcinoma (1 paper, 2024). A carcinoma that arises from the intrahepatic biliary tree (intrahepatic cholangiocarcinoma) or from the junction, or adjacent to the junction, of the right and left hepatic ducts (hilar cholangiocarcinoma). "They further found that SPRY4 promoted cholangiocarcinoma progression by promoting cancer cell proliferation rather than by inhibiting cancer cell apoptosis." (PMID 38686189, 2024).
choriocarcinoma (1 paper, 2018). An aggressive malignant tumor arising from trophoblastic cells. "Furthermore, the SPRY4 and SPRY4-IT1 RNA levels in yolk sac tumour, embryonal carcinoma, and teratoma were considerably higher than those in choriocarcinoma and seminoma." (PMID 29410498, 2018).
colon adenocarcinoma (1 paper, 2023). "An increase in SPRY4 transcripts was identified in patients with colon adenocarcinomas compared to both adjacent colon and healthy mucosa controls (GSE166427)." (PMID 36384366, 2023). "Overall, two separate CRC gene expression studies and CRC patients analysed in TCGA revealed increased SPRY4 mRNA expression in colon adenocarcinomas." (PMID 36384366, 2023). "Hence, the existing 5hmC next-generation sequencing profiles from colon adenocarcinomas and matched control tissues were parsed to examine changes in 5hmC levels within the promoter and gene body of SPRY4." (PMID 36384366, 2023). "However, a decrease of 5hmC within the gene body of SPRY4 was detected in colon adenocarcinomas." (PMID 36384366, 2023).
ductal carcinoma in situ (1 paper, 2024). "SPRY4 was highly expressed in ductal carcinoma in situ and decreased with the transition to invasive ductal carcinoma." (PMID 38686189, 2024).
embryonal carcinoma (1 paper, 2018). A non-seminomatous malignant germ cell tumor characterized by the presence of large germ cells with abundant cytoplasm resembling epithelial cells, geographic necrosis, high mitotic activity, and pseudoglandular and pseudopapillary structures formation. "SPRY4 expression levels were higher than those of SPRY4-IT1 in yolk sac tumour, embryonal carcinoma, and choriocarcinoma, whereas SPRY4-IT1 expression levels were higher than those of SPRY4 in teratoma." (PMID 29410498, 2018).
hearing loss (1 paper, 2021). "DUSP6 (Dual Specificity Phosphatase 6; chr 12q21.33) and SPRY4 (Sprouty RTK Signaling Antagonist 4; chr 5q31.1) are repressors of the FGF8/FGFR1-activated MAPK cascade and pathogenic variants were found in patients with either normosmic CHH and KS together with hearing loss." (PMID 34502334, 2021).
hilar cholangiocarcinoma (1 paper, 2024). A cholangiocarcinoma that arises from the junction, or adjacent to the junction, of the right and left hepatic ducts. "The molecular mechanism by which SPRY4 exerts anti-cancer effects in perihilar cholangiocarcinoma is mainly related to ERK phosphorylation, which inhibits cell proliferation and migration." (PMID 38686189, 2024). "In conclusion, SPRY4 may act as a tumor suppressor in hilar cholangiocarcinoma by regulating ERK phosphorylation and affecting cell proliferation and migration, thereby impacting the malignancy of the tumor." (PMID 38686189, 2024).
Infertility (1 paper, 2017). "Our RNA profiling data strongly support the theory that in the high infertility risk group of cryptorchid boys insufficient PROK2/CHD7/FGFR1/SPRY4 gene expression, together with observed deficient EGR4 and PITX1 signaling, induce deficient LH secretion, which results in impaired mini-puberty." (PMID 29163975, 2017).
ischemic disease (1 paper, 2024). Lack of blood supply to an area of the body, resulting in impairment of tissue oxygenation. "SPRY4 is also involved in organ development and is associated with ischemic diseases." (PMID 38686189, 2024).
lentivirus infection (1 paper, 2022). Virus diseases caused by the Lentivirus genus. "In order to prove that the function change caused by miR-92a overexpression is due to the SPRY4 downregulation, we constructed the miR-92a stable overexpression NSCLC cell models by pLenti-miR-92a or pLenti lentivirus infection." (PMID 35484993, 2022).
metastatic tumors (1 paper, 2016). "Thus, the increased malignant phenotype due to loss of Spry4 was maintained in vivo in primary tumors as well as secondary, metastatic tumors." (PMID 26973433, 2016).
small cell carcinoma (1 paper, 2025). A neuroendocrine carcinoma composed of small malignant cells which are often said to resemble "oat cells" under the microscope. "Therefore, we selected the DMS114 cell line, a small cell carcinoma-derived cell line, known to have an amplification at the genomic locus harbouring FGFR1 gene, to perform growth experiments comparing the two Spry4 variants." (PMID 40806483, 2025).
triple-negative breast carcinoma (1 paper, 2021). An invasive breast carcinoma which is negative for expression of estrogen receptor (ER), progesterone receptor (PR), and human epidermal growth factor receptor 2 (HER2). "Of clinical relevance, epigenetic therapy approaches that alter the expression of genes with the broad epigenetic domain must be cognizant that silencing these genes may make the cancer more aggressive as shown with SPRY4 in triple negative breast cancer." (PMID 34238359, 2021).
virus infection (1 paper, 2022). "qRT-PCR and western blotting showed that SPRY4 expression was upregulated effectively after the lenti-SPRY4 virus infection." (PMID 36082406, 2022).